ADHFE1 (alcohol dehydrogenase iron containing 1)
Diseases named in the same sentence as ADHFE1 in open-access papers (continued):
Sharing a sentence is not in itself a finding about the gene and the disease.
cancer (13 papers, 2014 to 2023). A tumor composed of atypical neoplastic, often pleomorphic cells that invade other tissues. "Alcohol dehydrogenase iron containing 1 (ADHFE1) encoded hydroxy acid-oxyacid trans-hydro enzymes involved in a variety of biological processes, including cancer." (PMID 36969015, 2023). "Herein, we performed data analysis to investigate the expression of ADHFE1 and the underlying regulatory mechanisms, its relationship with cancer patients’ survival, and the relevant pathways in cancer." (PMID 34179501, 2021). "In summary, our findings demonstrated that ADHFE1 expression is regulated by DNA methylation and can be a promising diagnostic and prognostic biomarker in cancer." (PMID 34179501, 2021). "Next, we investigated the association between the expression level of ADHFE1 and patient survival in various cancers using R2 and SurvExpress." (PMID 34179501, 2021). "In the past, the promoter hypermethylation of ADHFE1 or ALDH1A2 was identified as a common issue in cancers and served as a risk factor with a poor prognosis." (PMID 32238162, 2020). "More recently, the downregulation of the ADHFE1 gene has been linked to decreased cancer survival." (PMID 35054365, 2022). "Therefore, in the present study, we have systematically analyzed ADHFE1 expression and the underlying regulatory mechanisms in various cancers through several recognized expression databases and bioinformatics tools." (PMID 34179501, 2021). "Compared with HOXA5, the better discrimination of normal and cancer tissues by ADHFE1 signifies the great potential for this gene as a methylation marker to indicate pathological changes." (PMID 35054365, 2022). "We found that ADHFE1 was frequently downregulated and hypermethylated in various cancer cell lines and tissue samples." (PMID 34179501, 2021). "In this study, we systematically examined the expression of ADHFE1 and the regulatory mechanisms of ADHFE1 expression in cancer cell lines and tissue samples." (PMID 34179501, 2021). "In the previous studies, ADHFE1 has been shown to be closely related with the tumorigenesis and progression of many cancers." (PMID 34760694, 2021). "We used the Correlate Gene function to find genes significantly correlated with ADHFE1 expression in each cancer type (|Pearson coefficient| >0.3 and P-value <0.05)." (PMID 34179501, 2021). "Next, we examined the expression pattern of ADHFE1 across a range of cancer samples using the Oncomine database." (PMID 34179501, 2021). "IPA enrichment analysis of hyper-DMRs identified in very early stage cancers selected Ethanol degradation II as the top term for functional impact, in which ADHFE1 and ACSS3 were hit." (PMID 32317010, 2020). "On the other hand, the hypermethylation of ADHFE1 further reduced the expression of neighbouring proteins, ADH6, ADH7, as well as ADH1A, in which the genes were associated with the patient’s prognosis and cancer pathogenesis." (PMID 35054365, 2022). "Dysregulation of ADHFE1 was observed in several types of human cancer, and DNA methylation might be a major contributor." (PMID 34179501, 2021). "Several studies have also shown that ADHFE1 was involved in cancer development." (PMID 34179501, 2021). "Finally, we set to explore potential signaling pathways and biological processes related to dysregulated ADHFE1 expression in cancer." (PMID 34179501, 2021). "Finally, ADHFE1-associated pathways and biological processes were explored to unveil the potential functions and molecular mechanisms of ADHFE1 in cancer." (PMID 34179501, 2021). "Thus, we first investigated ADHFE1 expression and DNA methylation in the NCI-60 cell line set using the CellMiner database to explore the possible role of ADHFE1 in cancer tentatively." (PMID 34179501, 2021).
cancer (continued). "Consistent with previous findings, downregulation and hypermethylation of ADHFE1 were found in some of the cell lines of the nine cancer types included in the CellMiner database, and a negative correlation between DNA methylation and mRNA expression of ADHFE1 was observed." (PMID 34179501, 2021). "Dysregulation of ADHFE1 is involved in pathways, including energy metabolism, DNA replication, and cell cycle regulation, among others, suggesting its potential role in active biological processes related to cancer progression." (PMID 34179501, 2021). "Finally, we identified genes correlated with ADHFE1 shared by the three selected cancers, based on which gene enrichment analysis was performed to explore ADHFE1 affected pathways." (PMID 34179501, 2021). "Likewise, we found a number of genes whose expression follows this pattern: late-stage cancers < early-stage cancers < normal tissue, such as ADHFE1, LOC653501, NT5DC1, RSBN1, SOCS2 and TAPT1 in five cancer types." (PMID 28427185, 2017). "Interestingly, other than neomorphic isocitrate dehydrogenase (IDH) enzyme mutants found in many cancers, ADHFE1 is the only known enzyme to naturally produce (D)-2-hydroxyglutarate." (PMID 27383050, 2016). "Additionally, this study discovered that ADHFE1 might contribute to cancer progression through its interactions with signalling pathways such as energy metabolism, DNA replication, and the cell cycle." (PMID 35054365, 2022). "In previous studies, all four genes (ADHFE1, CNRIP1, MAFB, and TNS4) have been reported as cancer-related genes." (PMID 36158666, 2022). "We proposed that the contradictory role of ADHFE1 in differing cancer types might be attributed to its multiple roles in cellular functionalities (such as metabolic reprogramming, DNA replication, and cell cycle control), which depend on the cancer type and cellular status." (PMID 34179501, 2021). "To validate our findings in the Oncomine database, we inquired the expression of ADHFE1 in GENT, another standard online bioinformatics platform providing the expression patterns of genes across a wide range of cancer and normal tissues." (PMID 34179501, 2021). "We found that the average methylation level of CpG sites located in CpG islands within the promoter regions of ADHFE1 and ACSS3 were significantly increased in cancer samples compared to normal samples (∆mBVs = 0.2 and 0.18, respectively)." (PMID 32317010, 2020). "Of note, HAAO, MGLL, and UPGE were down-regulated in 18 cancer types; ADHFE1, CAT, and MSRA were down-regulated in 19; and RGN was down-regulated in 21 different types of cancer." (PMID 31351478, 2019). "ADHFE1, hypermethylated in 98.13% of the 268 CRC samples, was hypermethylated and downregulated in all the 16 cancer tissues compared with their paired adjacent normal tissues." (PMID 28537885, 2017). "Next, we performed the analysis with cancer tissue samples in the Oncomine and GENT databases and revealed that expression of ADHFE1 is commonly downregulated in cancer tissues compared with normal tissues, suggesting ADHFE1 as a promising diagnostic biomarker in cancer." (PMID 34179501, 2021). "ADHFE1 and ALDH1A2 have been reported to be downregulated and hypermethylated in cancers." (PMID 32238162, 2020).
ADHFE1 also shares sentences with these, for which no sentence is quoted: breast invasive carcinoma (2 papers); glioblastoma (2); adenocarcinoma (1); alcohol addiction (1); brain tumors (1); colon adenocarcinoma (1); esophageal adenocarcinoma (1); head and neck squamous cell carcinoma (1); hepatocellular carcinoma (1); kidney cancer (1); lung adenocarcinoma (1); lymphoma (1); Obesity (1); prostate adenocarcinoma (1); stomach cancer (1); T cell lymphomas (1); thyroid carcinoma (1); tongue squamous cell carcinoma (1); triple-negative breast carcinoma (1).